CD81 (CD81 molecule)
Diseases named in the same sentence as CD81 in open-access papers (continued):
Sharing a sentence is not in itself a finding about the gene and the disease.
infection (167 papers, 2005 to 2025). The state of being infected such as from the introduction of a foreign agent such as serum, vaccine, antigenic substance or organism. "Although this study provides meaningful information on the so far unexpected role of surface-associated CD81 during Mab infection, there are some limitations that should be addressed in future studies." (PMID 36818301, 2023). "Over the course of infection, only one mutation in the surface glycoprotein E2 consistently reverted to wildtype, facilitating assembly in cell culture but potentially affecting CD81 interaction in vivo." (PMID 35763545, 2022). "Low CD81 levels in the HIV-1 envelope are also associated with an enhanced viral titer in subsequent T cell infections, potentially due to an enhanced ability for viral entry." (PMID 34769038, 2021). "For instance, CD9 and its related tetraspanin, CD81, are localized in the growing tips of virus buds and involved in the infection cycle, and are directly implicated in generating membrane curvature." (PMID 32231207, 2020). "Nevertheless, three of the five tested variants, namely A54V, V211M and M220I, are less susceptible to infection with HCVcc genotypes 2, 3, 4 and 5 in comparison to WT CD81-expressing cells." (PMID 32322956, 2020). "In particular, CD81 is essential for infection with both pathogens as mice are only susceptible to HCV when expressing human CD81 and blocking CD81 on human hepatocytes impairs P. falciparum infection." (PMID 30024968, 2018). "Mutations within or adjacent to the CD81 contact site were observed in both patients but were less frequent and more conservative in the patient that cleared his/her infection." (PMID 25970466, 2015). "In parallel, results of infection experiments of these two cell lines showed that infection was inhibited in cells expressing mutated CD81." (PMID 24509809, 2014). "Overall these results suggest that infection with the hepatitis C virus is associated with increase of soluble CD81." (PMID 22355327, 2012). "Here, we report that inoculation of Huh7.5 with natural virus causes productive infection, which can then be neutralized by α-CD81 antibodies." (PMID 21887279, 2011). "In particular, cells expressing higher levels of CD81 were found to be more susceptible to infection." (PMID 22174670, 2011). "In contrast preincubation of Jc1 variants with 10 μg/ml hCD81 LEL reduced infection by these viruses more than 10-fold, suggesting that both adapted variants are more susceptible to inhibition by soluble human CD81 protein." (PMID 20617177, 2010). "We adapted HCV to mouse CD81 and identified three envelope glycoprotein mutations which together enhance infection of cells with mouse or other rodent receptors approximately 100-fold." (PMID 20617177, 2010). "CD81 LEL is critical for the ability of CD81 to confer susceptibility to HCV glycoprotein-mediated infection." (PMID 18389082, 2008). "It suggests that CD81 upregulation may be partially linked to productive infection, while the modulation of other tetraspanins could reflect broader effects of the coculture microenvironment." (PMID 41322423, 2025). "Diverse human pathogenic alphaviruses require CD81 for efficient infection." (PMID 35612284, 2022). "Furthermore, infection of 253G1 cells with HCV-JFH1-tau Lot B1 having M706L mutation was blocked by anti-CLDN6 antibody as well as anti-CD81 and anti-OCLN antibodies." (PMID 36424447, 2022). "Interestingly, maintenance of highly-replicating HCV stable cells led to decreased susceptibility to HCV pseudotyped particle (HCVpp) infection and downregulated cell surface level of CD81, a critical HCV entry (co)receptor." (PMID 23349980, 2013). "To assess if increased binding of Jc1/mCD81 to human CD81 correlates with altered receptor usage during virus entry, we used two complementary approaches: First, we analyzed susceptibility of Jc1/mCD81 infection to neutralization with anti-human CD81 antibodies." (PMID 20617177, 2010).
infection (continued). "Human OCLN was also able to render mouse cells susceptible to HCVpp infection, along with expression of human CD81, suggesting that OCLN may be a species-restricting determinant of HCV infection." (PMID 21994703, 2010). "Thus, the inability of 5A6 to inhibit infection while interacting with a critical region of CD81 is consistent with the hypothesis that CD81 functions through the regulation of an associated protein." (PMID 18389082, 2008). "POL offers host resistance to virus entry and infection by blocking CD81 and SR-B1 receptors on host cells." (PMID 40739150, 2025). "The transmembrane proteoglycan Syndecan-1 and RhoA are involved in the infection process through the CD81." (PMID 39745447, 2025). "The inhibition of PHEV-VW572 infection following neutralizing antibody or siRNA treatment suggests that CD81 is the main receptor for the virus in neuronal cells." (PMID 41059972, 2025). "Occludin also maintains hepatocyte polarity and enhances infection efficiency by promoting the co-localization of the CD81/Occludin receptor complex." (PMID 40142587, 2025). "As proof of concept, we targeted the hepatocyte tetraspanin CD81, a critical host factor for hepatocyte infection by P. falciparum sporozoites, with a specific siRNA." (PMID 40677836, 2025). "In vitro stimulation with CD9+ CD81+ exosomes from DENV-2 NGC-infected cells favored the infection of naïve cells, indicating their ability to transmit virus." (PMID 39754219, 2025). "They show that in vivo liver knockdown of CD81 blocks parasite liver infection, preventing the occurrence of symptomatic blood stage infection." (PMID 40677836, 2025). "Infection with a high inoculum of HIV increased the expression of the co-receptor CCR5, as well as the tetraspanins CD9 and CD81, which correlated with deficient osteoclastogenesis." (PMID 37404829, 2023). "Two variations of the HC-04 cell line for P. falciparum were compared for infection efficiency; the wild-type HC-04, and the modified HC-04 which was engineered to express elevated levels of both CD81 and EphA2 receptors." (PMID 36928885, 2023). "To determine if increasing these receptor levels would improve infection rates in our ectopic huLiver model, we generated a HC-04 cell line with higher expression of both EphA2 and CD81; HC-04 EphA2High CD81 High." (PMID 36928885, 2023). "Future studies should be dedicated to understand how Mab regulates expression of AhpC to drive the interaction with CD81 during infection." (PMID 36818301, 2023). "Both routes of infection require expression of the receptor complex (CD81, scavenger receptor BI, claudin-1 and occludin)." (PMID 37750869, 2023). "The expression levels of co-receptors CCR5, CD9, and CD81 were measured before and after infection with HIV." (PMID 37404829, 2023). "Lastly, CD81 expression enhanced infection with the New World alphavirus VEEV by 6-fold compared to parental cells." (PMID 35612284, 2022). "Infection kinetics showed that 48 h postinfection, only 15% of parental Lunet N#3 cells but more than 90% of CD81-expressing cells were infected." (PMID 35612284, 2022). "(D) Kinetics of WT and mutant HCV entry were experimentally measured by synchronised infection of Huh-7.5 cells by HCVpp, followed by chase with a saturating inhibitory concentration of anti-CD81 mAb." (PMID 35796426, 2022). "As expected, Lunet N#3 cells were poorly permissive to CHIKV (LR2006-OPY1 strain) infection, and expression of wild-type CD81 resulted in a marked increase in CHIKV infection." (PMID 35612284, 2022). "To assess the presence of infectious virus, we used Huh7-Lunet CD81 cells stably expressing the MAVS-GFP-NLS reporter allowing for a sensitive detection of infection events in living cells." (PMID 35763545, 2022). "To assess the role of CD81 in full-length genome replication, we infected cells with a luciferase reporter virus (181/25 strain) and monitored infection kinetics between 2 h and 10 h." (PMID 35612284, 2022).
infection (continued). "The results showed that IND02 markedly inhibited the first stage of infection in a way that overlapped with the inhibitory activity of the anti-CD81 antibody that targets the HCV cell entry factor CD81." (PMID 36500445, 2022). "For example, CD81 neutralizing antibodies support fusion of mouse macrophages infected with B. thailandensis, whereas inhibition of CD81 diminishes fusion upon infection with B. pseudomallei." (PMID 35478968, 2022). "Whilst ablation of CD81, Claudin-1 and Occludin abolished infection for all four tested strains, a proportion of all strains was still able to infect SR-B1 knock-out cells." (PMID 33147126, 2021). "The infectivities of VSV and MERS pseudoparticles were unaltered when made in 293TCD81KO cells, ruling out a general enhancement of pseudoparticle production; however, SARS-CoV-1/2pp infection was increased by ablation of CD81." (PMID 33147126, 2021). "Collectively, CD81 knock-down led to a twofold increase in infection for viruses in the panel indicating that the expression of CD81 in 293T cells affects HCVpp production." (PMID 33147126, 2021). "We consistently observed greater infection of Huh-7 cells for HCVpp produced in CD81 knock-down 293T cells (CD81-2) compared to their E1E2 matched equivalents produced in non-targeted pool siRNA (NTP-2) treated 293T cells." (PMID 33147126, 2021). "It is interesting that CD81-expressing human hepatoma HepG2 cells are permissive to productive infection by sporozoites of the rodent parasites P. berghei and P. yoelii, but not to productive infection by P. falciparum." (PMID 34268141, 2021). "Pre-treatment of Huh7.5 with anti-CD81 antibody or limonoids significantly (p˂0.05) prevented infection with 100 TCID50 of Jc1/Gluc2A as shown by IFA for HCV core detection and GLuc2A activity compared to DMSO control." (PMID 34290967, 2021). "Pre-treatment of J774.2 macrophages with GST-EC2s corresponding to CD9, CD63, and CD81 significantly suppressed MNGC formation on infection with both E264 and CDC272 strain of B. thailandensis." (PMID 32253503, 2020). "It will be of interest to determine the effect of CD9 or CD81 on MNGC formation during infection with B. pseudomallei T6SS-5 and VgrG5 mutants in future studies." (PMID 33087788, 2020). "Overall, we demonstrate that targeting host factors that regulate endocytic compartments and vesicle trafficking to the plasma membrane within MDDC results in the disruption of trafficking of CD81 and virus to the VS reducing trans-infection." (PMID 32075937, 2020). "A significant enhancement of MNGC formation following treatment of J774.2 and RAW264.7 cells with anti-CD9 and anti-CD81 mAb prior to infection with B. thailandensis was observed." (PMID 32253503, 2020). "CD81 plays an important role in regulating viral trans-infection at the VS, and depletion of the tetraspanin can reduce viral trans-infection." (PMID 32075937, 2020). "We also used flow cytometry to investigate the early changes in the cell surface expression of these proteins and tetraspanins CD9 and CD81 following infection." (PMID 32253503, 2020). "Huh-7.5 cells were pre-incubated with anti-SR-B1 or anti-CD81 antibodies that are capable of inhibiting E2-receptor interaction and preventing infection." (PMID 30883541, 2019). "Here, we provide the inferred proportion of viruses that acquire sufficient CD81, that complete downstream steps of entry and that achieve productive infection." (PMID 30883541, 2019). "Our model estimates the probability that a single virus founds a productive infection under varying availability of CD81 and SR-B1." (PMID 30883541, 2019). "We used the model to investigate the effect of co-varying SR-B1 and CD81 availability; in effect, this enables in silico infection assays to be performed with arbitrary receptor availability." (PMID 30883541, 2019).
infection (continued). "Our results show a clear difference between the two receptors; while an absolute blockade of CD81 completely prevented infection, a similar blockade of SR-B1 allowed a small proportion of viruses to achieve infection." (PMID 30883541, 2019). "Strain specific and broadly neutralising antibodies, which develop during natural infection, act by blocking E2-SR-B1/CD81 interactions." (PMID 30883541, 2019). "For instance when targeted individually our model predicts that a 50% inhibition of infection would require 70–80% of SR-B1/CD81 molecules to be successfully blocked." (PMID 30883541, 2019). "Downstream events leading to productive infection are then even less efficient, with close to 4% of particles which gain sufficient CD81 completing these steps." (PMID 30883541, 2019). "We also tested if the requirement for entry co-receptors CD81 and SR-BI to establish infection was altered in HCV derived from the bioreactors." (PMID 30504788, 2018). "Our experiments with siRNA-mediated knockdown of CD9 and CD81 in HeLa cells highlighted the importance of both tetraspanins in HPV16-mediated infection." (PMID 30279342, 2018). "Exposure of Huh7.5.1 monolayers to the 67-2 mAb resulted in significant reduction in infection with HCVpp; however, the effectiveness was weaker than that of anti-CD81 mAb." (PMID 29682171, 2018). "We next measured the impact of EphA2 silencing on CD81-dependent infection using GFP-expressing P. yoelii parasites (PyGFP)." (PMID 29975762, 2018). "Following infection with PbGFP sporozoites, cells were recovered at 24 hours post-infection, labeled with anti-EphA2 or anti-CD81-antibodies and analyzed by FACS." (PMID 29975762, 2018). "HCVcc, sf-HCVcc, HCVHFBR and sf-HCVHFBR showed similar dependency on co-receptor CD81 as antibody-mediated blocking of co-receptor CD81 resulted in 88–95% blocking of infection." (PMID 30504788, 2018). "Further studies are needed to elucidate the function of CD81 and SR-BI during infection and to unravel the molecular interactions leading to parasite host cell invasion in the liver." (PMID 29975762, 2018). "For instance, CD81 is required for human Plasmodium falciparum and rodent Plasmodium yoelii sporozoite hepatocyte infection." (PMID 29765366, 2018). "Whilst P. falciparum, like P. yoelii, relies on CD81 for infection, P. vivax sporozoites enter hepatocytes via a SR-BI-dependent pathway." (PMID 29975762, 2018). "Conversely, the CD81 region required for infection of hepatocytes by Plasmodium yoelii (a rodent parasite) sporozoites is unaffected by selection." (PMID 29765366, 2018). "In order to confirm these findings in another cell type, we analyzed the effects of EphA2 silencing in HepG2/CD81 cells, using flow cytometry to quantify PyGFP-infected cells 24 hours post-infection." (PMID 29975762, 2018). "P. berghei sporozoites infect mouse hepatocytic Hepa1-6 cells via a CD81-dependent pathway, as shown by efficient inhibition of infection by CD81 specific antibodies or siRNA." (PMID 28506360, 2017). "We therefore assessed the effect of BUD, FLUT, and AZI treatment on the release of CD63+/CD81+ host cell vesicles by macrophages under control conditions and upon infection." (PMID 28528362, 2017). "Previous studies have identified CD81 and SR-BI as important host factors for infection of hepatocytes." (PMID 28506360, 2017). "Anti-CD81 antibody was efficient at inhibiting JFH1 infection of pancreatic islet cells at a 1:00 dilution, although a 1:2500 dilution had no inhibitory effect compared to the IgG control condition." (PMID 29258547, 2017). "Remarkably, transfection of either human CD81 or human SR-BI was sufficient to rescue infection in CD81-silenced cells, demonstrating that the two receptors can independently perform the same function to support P. berghei infection." (PMID 28506360, 2017).
infection (continued). "Other genes in this network associated with immunity and infection were toll-interleukin 1 receptor (TIR) domain containing adaptor protein, CD38 molecule, CD48 molecule, CD81 molecule, inducible T-cell co-stimulator ligand." (PMID 29302351, 2017). "By contrast, CD81 and SR-BI fulfil redundant functions during infection by the rodent parasite P. berghei." (PMID 28506360, 2017). "We used a cell line defective in the virus entry factor, CD81, thus excluding the possible effect of secondary infection and allowing analyses in a single cycle infection setting." (PMID 27406141, 2016). "We also compared manual FFA to Infection Counter for calculating the inhibitory activity of HCV receptor-blockade by anti-CD81 mAb." (PMID 27455304, 2016). "To investigate the receptor dependency of cell infection, we assessed the ability of an antibody specific of CD81 to inhibit HCVpp-h77 or HCVpp-JFH1 infection." (PMID 26214688, 2015). "Infection of cholangiocarcoma cells was inhibited by antibodies specific for CD81, SR-BI, E2 glycoprotein and by pooled immunoglobulin from chronic HCV infected patients." (PMID 25701818, 2015). "As infection progresses, the dependence on CD81 is reduced and viral subpopulations with low affinity binding are selected because they allow entry but would simultaneously make this region a subdominant neutralization epitope." (PMID 25970466, 2015). "Both IL-1β and TNF-α increased HCVpp (strain H77) infection of polarized HepG2.CD81 cells, whereas IFN-γ reduced infection in a dose-dependent manner." (PMID 24259385, 2014). "No inhibition was obtained with HLy9.1.25 mAb, whereas the positive control, JS-81 anti CD81 antibody inhibited infection up to 90%." (PMID 24927415, 2014). "In contrast, activated macrophages promote infection of polarized cells through the production of TNFα that increases membrane diffusion of CD81." (PMID 24509809, 2014). "CM was collected and assessed for its effect on HCV pseudoparticle (HCVpp) infection of polarized HepG2.CD81 cells." (PMID 24259385, 2014). "HCV infection led to down-regulation of GP73 in Huh7 and HepG2/CD81 cells at the early stage of infection." (PMID 24351813, 2013). "About half of the influenza virus particles that fused in cells underwent fusion within CD81+ endosomes, and CD81 depletion led to a decrease in virus fusion and infection." (PMID 24130495, 2013). "This infection was inhibited by anti-CD81 antibody in a similar concentration-dependent manner as in vitro infection of JFH-1." (PMID 24358200, 2013). "Inhibition of HCVcc infection and HCVpp entry by QV-6A8-F2-C4 was in a similar range as inhibition of infection by the commercially available anti-CD81 mAb JS81 (IC50s of 0.5 and 2 μg/ml, respectively)." (PMID 23704981, 2013). "Transfection of cells with J6/JFH1 viral genome not only led to a higher degree of CD81 reduction on the cell surface but also rendered cells more refractory to HCVpp infection as compared to those of JFH1-transfected cells." (PMID 23349980, 2013). "In contrast, polarized HepG2 expressing wild-type or mutant CD81 supported comparable rates of infection." (PMID 23126643, 2013). "Synchronized infection assays showed that glycosaminoglycans and SR-BI mediated host cell binding, while CD81, CLDN1 and OCLN all acted sequentially at a post-binding stage prior to endosomal acidification." (PMID 23555257, 2013). "These mutants were expressed in polarized HepG2 cells engineered to support the complete HCV life cycle by CD81 and miR-122 expression and synchronized infection assays were performed to define the kinetics of HCV cell entry." (PMID 23555257, 2013). "In this work, we dissected the roles of CD81 on individual steps along the infection pathway from virus entry to egress." (PMID 24130495, 2013). "The anti-CD81 mAbs efficiently inhibited infection by HCV of different genotypes as well as a HCV escape variant selected during liver transplantation and re-infecting the liver graft." (PMID 23704981, 2013).